MIR1226 (microRNA 1226)
Synonyms: hsa-mir-1226; MIRN1226; mir-1226
Gene: MicroRNA gene on chromosome 3 (47,849,555 to 47,849,629, forward strand). Ensembl gene ENSG00000221585.
Gene Ontology:
Biological process: miRNA-mediated post-transcriptional gene silencing
Homologues: Orthologues: chimpanzee ptr-mir-1226 (100% identical), macaque mml-mir-1226 (100% identical).